KRAS (KRas proto-oncogene, GTPase)
Diseases named in the same sentence as KRAS in open-access papers (continued):
Sharing a sentence is not in itself a finding about the gene and the disease.
tumor (continued). "KRAS mutations were detected in 37 (33%), BRAF mutations in eight (7.2%) and PIK3CA mutations in 11 (9.8%, 8 in exon 9 and 3 in exon 20) primary tumours, respectively." (PMID 21283802, 2011). "Other important facts about KRAS testing are the correct evaluation of the amount of tumour tissue in the sample and the sensitivity of testing methods." (PMID 21364579, 2011). "Results from this and previous studies therefore suggest that EBUS-TBNA can provide sufficient tumour material for EGFR and KRAS mutation analysis in routine clinical practice thus avoiding the need for more invasive surgical sampling in these patients." (PMID 21949883, 2011). "In the present study, we investigate KRAS and EGFR mutation status using PCR-based sequencing analyses in 80 primary tumor samples and their corresponding local lymph node metastases from Chinese patients with NSCLC." (PMID 21414214, 2011). "A recent meta-analysis demonstrated 3% rate of objective tumor response to EGFR TKIs in patients with KRAS mutations, as compared to 26% in those with wild-type KRAS." (PMID 21444946, 2011). "KRAS and BRAF mutations were mutually exclusive, whereas, three tumours carried both KRAS and PIK3CA mutations." (PMID 21283802, 2011). "As previously reported, we identified amplification and over-expression of COX2 in KRAS mutant tumours." (PMID 21385341, 2011). "The difference in TTP between the patients with wt-KRAS and wt-BRAF tumours and the patients with wt-KRAS and mt-BRAF tumours was 4 months." (PMID 22933967, 2011). "In this pathway, PIK3CA, KRAS and BRAF genes are frequently activated by mutations in various tumour types, including CRC with frequencies of 10–30%, 30–40% and 5–22%, respectively." (PMID 21673680, 2011). "Surgical resection of liver metastases was performed in 47/176 patients (26.7%); more specifically, in 31 patients with wt-KRAS tumours and in 16 patients with mt-KRAS tumours." (PMID 22933967, 2011). "A discordant KRAS status between the primary tumour and metastasis was observed in a small number of patients (3.6%)." (PMID 21364579, 2011). "Conversely, with the KRAS 73 primers the ctDNA concentration highly increased in parallel with tumour weight." (PMID 21909401, 2011). "It is possible that acquisition of a mutation, such as KRAS or BRAF, represents the moment of transition from a benign tumour to an LMP." (PMID 22163003, 2011). "These biomarkers primarily focus on target biomarkers in tumours that predict patient response, although, more recently, tumour biomarkers of resistance have also been employed, as with mutant KRAS in EGFR-directed therapies." (PMID 21649578, 2011). "The objective response rates in the group of patients with wt-KRAS and wt-BRAF tumours were 54.0% (CR 14.7%, PR 39.3%), while in the group of patients with wt-KRAS and mt-BRAF were 38.5% (CR 15.4%, PR 23.1%)." (PMID 22933967, 2011). "Engelman and colleagues recently reported that the combination of PI3K and MEK inhibitors led to marked synergistic tumor regression in KRAS-mutant mouse lung tumors." (PMID 21124782, 2010). "The frequency of mutations for KRAS, PIK3CA, and BRAF were tested for correlation to the degree of differentiation and to the prevalence of mucin in the tumor." (PMID 20233444, 2010). "Often linked to tumours arising from the chromosomal instability pathway, representing 80–85% of CRC cases, KRAS mutations have been associated with increased activity of ERK signalling, thereby promoting transcription of Elk-1 and c-Myc." (PMID 19935791, 2010).
tumor (continued). "The mutant status of KRAS and SMAD4 gene was found to be significantly associated with the higher tumor grade (C+D) (P value = 0.03)." (PMID 20565773, 2010). "In clinical practice, our algorithm for KRAS analysis includes a reanalysis of samples with low tumor cell content (< 10%, n = 56) using an independent assay (allele-specific PCR, DxS)." (PMID 21122130, 2010). "CIMP subgroups were compared for various clinicopathological and molecular features including patient age, tumor site, microsatellite instability (MSI), methylation at a consensus panel of CpG islands and mutations in BRAF and KRAS." (PMID 20492682, 2010). "Objectives of the study were to correlate the GCN and KRAS status with the pathological response according to Dworak's tumour regression grade (TRG), DFS and overall survival (OS)." (PMID 20842128, 2010). "Downstream of KRAS in ERK/MAPK signalling lies BRAF, a gene that in sporadic disease is mutated in ∼10% of CRC and is more highly associated with tumours showing microsatellite instability (MSI)." (PMID 19935791, 2010). "The European Medicines Agency has also recognised these findings, and indeed also restricts the use of anti-EGFR antibody therapy only to CRC patients with wild-type (wt) KRAS tumours." (PMID 20959826, 2010). "Response rates in patients that do not harbor an activating mutation in EGFR are low, and mutations in KRAS and EGFR rarely occur in the same tumor." (PMID 20591134, 2010). "A discordance between primary tumours and distant metastases was observed for KRAS in 10% of the cases and for PIK3CA in 5% of the cases." (PMID 21139621, 2010). "We next assessed if the COLD-PCR enhanced melting curve assay was sensitive enough to eliminate the need for tumor dissection in a KRAS-mutant sample with a low percentage (~3%) of tumor cells." (PMID 21110880, 2010). "In other words we can say that the tumor which has SMAD4 mutant status is also likely to have KRAS gene mutant status." (PMID 20565773, 2010). "A third group reported equivocal KRAS results in 10% (18/180) of FFPE tumor specimens using a melting curve approach that was similar to our assay without COLD-PCR enhancement." (PMID 21110880, 2010). "Tiny allele amounts of mutated KRAS suggest a majority of wild type cells concerning the KRAS gene in the tumor." (PMID 21197450, 2010). "One of the main subjects of debate is the relevance of KRAS genotyping on primary tumours, whereas anti-EGFR mAbs are used to treat a metastatic disease." (PMID 21139621, 2010). "As reviewed by Fakih and Wong in this supplement, the efficacy of the anti-EGFR antibodies cetuximab and panitumumab in the treatment of mCRC has consistently been shown to rely on the KRAS status of the tumor." (PMID 20680106, 2010). "As these rare KRAS mutations and BRAF mutations are mutually exclusive with the others, it seems reasonable to test for their presence only in patients with KRAS codon 12 and 13 wild-type tumours." (PMID 19603018, 2009). "PCR-based assays constitute the cornerstone for clinical KRAS testing since these analyses allow high-throughput testing and have a favorable sensitivity, also in samples with low tumor cell content." (PMID 19832985, 2009).
tumor (continued). "This phase II, open-label, single-arm trial was designed to prospectively estimate the efficacy of panitumumab plus FOLFIRI treatment as a function of tumor KRAS status in patients undergoing second-line treatment for metastatic CRC." (PMID 19386128, 2009). "A recent development in this context concerns two anti-EGFR antibodies, cetuximab and panitumumab, that have been labeled for use in metastatic colorectal cancer (CRC) under the condition that the tumor carries a wild-type KRAS gene." (PMID 19888477, 2009). "We determined with confidence the mutational status for KRAS exon 2, BRAF exon 15, and PIK3CA exons 9 and 20 in 168 consecutive patients with mCRC, for whom a representative sample from the primary tumour was available for molecular analysis of DNA." (PMID 19603024, 2009). "To address the mechanism by which loss of RAS (KRAS in HCT116 and NRAS in IPC298) reduced cellular proliferation and delayed tumor growth, we analyzed cell cycle progression and apoptosis induction in these cells following dox treatment." (PMID 19492075, 2009). "Immunohistochemical analysis specifically detected KRAS in cancer cells (tumor D), whereas the expression of KRAS in adjacent noncancerous cells was below the level of detection." (PMID 19545448, 2009). "KRAS mutations were detected in 62 (37%), BRAF mutations in 13 (8%) and PIK3CA mutations in 26 (15%, 18 in exon 9 and 8 in exon 20) primary tumours, respectively." (PMID 19603024, 2009). "We determined KRAS, BRAF and PIK3CA mutations in tumours from 168 patients treated for mCRC at two institutions." (PMID 19603024, 2009). "All KRAS, BRAF, and EGFR mutations were mutually exclusive across different tumor types while some PIK3CA mutant cases also harbored one of the other three mutations." (PMID 19826477, 2009). "In the present analysis, 13, 7 and 1 patient among 87 patients with KRAS codon 12 and 13 wild-type disease had tumour bearing BRAF V600E, KRAS codon 61 and KRAS codon 146 mutation, respectively." (PMID 19603018, 2009). "Other studies have pointed to a tumor suppressor role of miR-143 in colon, and other cancer cells, particularly through inhibition of KRAS, and ERK5 proteins." (PMID 19855844, 2009). "In the 10 studies that reported objective tumor response to cetuximab-containing therapy, the median RR in patients with KRAS WT tumors was 35% (range 12% – 42%) compared with 0% (range 0% – 6%) in patients with KRAS MT tumors." (PMID 19386128, 2009). "We retrospectively analyzed objective tumor response, progression-free (PFS) and overall survival (OS) together with the mutational status of KRAS, BRAF, PIK3CA and expression of PTEN in 132 tumors from cetuximab or panitumumab treated mCRC patients." (PMID 19806185, 2009). "In samples containing ≥10% tumor cells, detecting 1% mutant cells would correspond to genetic heterogeneity within the same tumor, as previously reported for KRAS in CRCs." (PMID 19888477, 2009). "OncoMap performance was assessed after determining the “ground-truth” mutational status at KRAS codon 12 using a DNA barcoding and massively parallel sequencing-by-synthesis strategy applied to 91 frozen and 93 FFPE-derived tumor DNAs." (PMID 19924296, 2009). "Tumour specimens of 178 NSCLC patients were collected and analysed for EGFR and KRAS mutation status by DNA sequencing, and for EGFR copy number by fluorescent in situ hybridisation." (PMID 19050706, 2009). "Tumours were obtained from patients of US (n=143) and Korean (n=167) origin and screened for LKB1, KRAS, BRAF, and EGFR mutations using RT—PCR-based SURVEYOR-WAVE method followed by Sanger sequencing." (PMID 18594528, 2008). "KRAS mutations were detected in 49 (16% in the whole tumour set, 25% in Caucasian and 8% in Asian specimens) tumour specimens with 10 (20% of KRAS mutants) of these occurring concurrently with an LKB1 mutation (P=0.042)." (PMID 18594528, 2008).
tumor (continued). "Tumour xenografts from both MDAH2774 (KRAS mutant) and SKOV3 (wild type of KRAS and BRAF) cell lines were established in a nu/nu mouse model." (PMID 19018267, 2008). "As our findings in NSCLC cell lines suggested concurrency of KRAS or BRAF and mutual exclusiveness of EGFR mutations with LKB1 mutations, we analysed the mutational status of these genes in our primary NSCLC tumour specimens." (PMID 18594528, 2008). "All mice injected with CI-1040 developed significantly smaller intra-abdominal xenograft tumours than the mice carrying diluent control cells of the KRAS mutant cell line MADH2774." (PMID 19018267, 2008). "In broader terms, one has to note that many of the tumours associated with PJS, including GI and gynaecologic malignancies are also those where KRAS is a frequent target of mutation." (PMID 18728656, 2008). "Four of the tumours harbouring either KRAS or BRAF mutations showed a marked reduction (<50% of DMSO control) in the cell number in the CI-1040-treated group as compared with the other 14 tumours containing wild-type KRAS and BRAF (P<0.001)." (PMID 19018267, 2008). "Further, whenever PIK3CA mutations occur in CRC they can occur in concomitance with activating KRAS-BRAF mutations, both in MSI and MSS tumours." (PMID 18782444, 2008). "In contrast to KRAS and PIK3CA mutations, BRAF mutations are associated with tumours harbouring CpG Island methylation phenotype (CIMP), MLH1 methylation and microsatellite instability (MSI)." (PMID 18782444, 2008). "The KRAS/LKB1 double knockout was in fact the most aggressive phenotype of all tumours considered in the study, and had an additional feature that had not previously been reported in a mouse model: squamous cell carcinoma histology." (PMID 18728656, 2008). "For instance, KRAS-driven tumors have been associated with neutrophil-rich inflammation and distinct metastatic behavior, while EGFR-mutated neoplasms frequently display “cold” immune phenotypes, characterized by low PD-L1 expression and reduced sensitivity to checkpoint blockade." (PMID 41517600, 2026). "In particular, KRAS mutation has been linked to shifts in the composition and functional state of tumor-infiltrating immune cells rather than to a uniform increase or decrease in global TIGIT/CD155 expression across the entire tissue." (PMID 41596586, 2026). "The inhibitory effect of cyAV3.3 on ABCG1 and KRAS in homospheroids might be due to the inhibitory effect of cell–cell interaction among tumor cells." (PMID 41584360, 2026). "Additionally, the growth and survival of KRAS-driven tumor cells are supported by G6PD through the maintenance of NADPH levels and antioxidant capacity." (PMID 41328353, 2026). "Co‐occurring mutations with smoking‐related canonical mutations, such as KRAS, STK11, and KEAP1, are common in patients with SMARCA4 mutations, and up to 44% of these patients exhibit a smoking‐related co‐mutation signature and a high tumor mutational burden." (PMID 41577374, 2026). "Furthermore, in vivo xenograft models confirmed that concurrent knockdown of murine KIF22 and KRAS effectively inhibited tumor progression." (PMID 41727639, 2026). "Despite its context-dependent biological duality, SMARCA4 mutations exert a more pronounced negative effect on KRAS G12Ci efficacy and immunotherapy response compared to other frequently co-mutated tumor suppressors." (PMID 41541668, 2026). "Somatic mutations in KRAS, NRAS, BRAF, and the occurrence of microsatellite instability (MSI) were assessed using pyrosequencing and real-time PCR assays, respectively, on formalin-fixed, paraffin-embedded tumour samples." (PMID 42279292, 2026).
tumor (continued). "Recent studies further demonstrate that KRAS-G12C inhibition leads to heterogeneous cellular responses, with subsets of tumor cells escaping via rapid re-synthesis of active, drug-insensitive KRAS protein, maintained through EGFR and Aurora kinase (AURK) signaling." (PMID 41526435, 2026). "However, recent studies have demonstrated that YAP/TAZ amplification alone is sufficient to bypass KRAS dependency and sustain tumor growth." (PMID 41550359, 2026). "A recent study has shown that a subset of individuals without cancer contain cells with KRAS oncogenic mutations, potentially leading to tumor formation." (PMID 41368203, 2026). "The functional impact of KRAS mutations in CRC depends on the specific amino acid substitution, as different mutations result in distinct biochemical and signaling alterations that influence tumor behaviors and therapeutic responses." (PMID 40361439, 2025). "Whole-exome sequencing revealed pathogenic KRAS and PIK3CA mutations in the MLA tumor." (PMID 41311737, 2025). "While KRAS inhibition blocks tumour growth, resistance may develop as cells adapt metabolically (they undergo a metabolic shift from anaerobic to aerobic arginine-dependent metabolism)." (PMID 40567499, 2025). "While these approaches are still in early stages, they offer a complementary strategy to directly target KRAS and may help overcome some of the challenges posed by the tumor microenvironment and resistance mechanisms." (PMID 40002297, 2025). "FOLFIRINOX therapy was associated with the longest OS for all patients regardless of the tumor KRAS mutation status, with a median OS of 12.2 (95% CI, 11.5-13.4) months for KRAS mutations and 18.5 (95% CI, 14.4-22.1) months for KRAS WT." (PMID 39777438, 2025). "Mutant KRAS promotes epithelial–mesenchymal transition (EMT), a process characterized by the loss of epithelial cellular adhesion and increased cellular motility, and suppresses immune surveillance to allow circulating tumor cells to colonize distant sites." (PMID 40361439, 2025). "Notably, rare residual progenitor-like cells retained high expression of these programs, suggesting incomplete KRAS inhibition or alternative mechanisms for sustaining tumor suppressive responses." (PMID 40661354, 2025). "PTTG genes, known for their involvement in cell cycle regulation, may synergize with EGFR and KRAS signaling pathways to promote tumor growth and aggressiveness." (PMID 40877987, 2025). "According to our previous report on the same cohort, cftDNA carrying KRAS point mutations in the G12, G13, and Q61 hotspots was significantly associated with such parameters as serum CA19-9 levels, presence of distant metastases, and the size of the tumor." (PMID 41009333, 2025). "We confirmed these findings in proliferation assays with KRAS WT–amplified cell lines derived from eight different tumor types and showed KRAS pathway modulation in these cell lines, indicating a clear correlation between signaling pathway modulation and growth inhibition." (PMID 39711431, 2025). "Furthermore, a KRAS c.35G>T (p.G12V) mutation with a VAF of 42.82% was detected in the specimen, which fits well with a tumor cell content of 80%." (PMID 40519304, 2025). "Preclinical studies suggest that KRAS-G12C inhibitors may enhance tumor immunogenicity, potentially synergizing with immunotherapies." (PMID 41200180, 2025). "Mutant KRAS upregulates the production of cytokines and chemokines, such as IL-6, CXCL8, and TGF-β, which recruit regulatory T-cells (Tregs), myeloid-derived suppressor cells (MDSCs), and tumor-associated macrophages (TAMs) to the TME." (PMID 40361439, 2025). "Beyond genetic mutations, PDAC can also be categorized into subtypes based on histology, gene expression, and the tumor microenvironment (TME), which may affect how mutations such as KRAS influence disease behavior and treatment response." (PMID 40805153, 2025).